IL5 (interleukin 5)
Diseases named in the same sentence as IL5 in open-access papers (continued):
Sharing a sentence is not in itself a finding about the gene and the disease.
tumor (continued). "Our results demonstrated that the mRNA expressions of IL-5, IL-1A, CXCL10, TNFSF4 and INHBE were significantly altered when regulating C1QTNF6, which suggested the essential implications of the cytokine-cytokine receptor interaction pathway in the process of C1QTNF6 regulating tumor progression." (PMID 35879698, 2022). "Likewise, treatment with the combination of IL-5 and GM-CSF blocking antibodies did not reverse the tumor-suppressing function of WT CD4+ T cells in Tslptg TslprKO mice." (PMID 35657353, 2022). "Thus, JAK3 promotes survival and proliferation of malignant T cells and expression of proto-oncogenes/oncomiRs and cytokines (IL-5, IL-9, IL-13, IL-17F and LTA), some of which are growth factor to malignant T cells while others modulate the tumour micro-environment (TME) and anti-cancer immunity." (PMID 33466582, 2021). "Interestingly, IL-5, IL-7, IL-20, and IL-22, rather than their receptors, have been widely reported to have the ability to predict tumor prognosis." (PMID 34497605, 2021). "Furthermore, release of Th2 cytokines, (i.e., IL-4 and IL-5) by basophils, mast cells and ILC2 may promote the recruitment of eosinophils and macrophages that control tumor progression." (PMID 33329534, 2020). "Reactive HE and HES (HER and HESR) aggregate all conditions (e.g., parasitic infections, adverse drug reactions, inflammatory, or neoplastic diseases) in which eosinophils are considered as non-clonal and are thought to be driven by Th-2 (mainly IL-5) cytokines." (PMID 29259972, 2017). "Furthermore, three of the prognostic cytokines/chemokines, CXCL9, IL-5, and TNF, when expressed at an increased level in specific tissue or cellular environment, may confer a downregulatory effect on tumor growth." (PMID 25825910, 2015). "Moreover, in mice lacking IL-5 or treated with anti-IL-5 antibody, the intravenous injection of B16-F10 cells resulted in the decrease in eosinophil infiltration and increase in lung tumor colonization compared with wild-type mice." (PMID 37508545, 2023). "Additionally, both IL-5 and GM-CSF could control tumor growth, since the negative regulation of IL-5 and GM-CSF has been shown to increase tumor burden in a murine model of CRC." (PMID 36296636, 2022). "Interestingly, ELAVL1 (HuR) was shown to modulate the expression of IL-5, IL-6, CCL-5, and TNF-alpha cytokines harboring the HuR-binding motif, which in consequence can influence the cross-talk between HRS cells and the immune infiltration in the tumor microenvironment." (PMID 33544339, 2021). "Indeed the use of intratumoral injections of IL-33 promotes antitumor activity of ILC2s either through IL-5 and GM-CSF, which control tumor growth, through the recruitment of eosinophils or through the production of CXCR2 ligands with lytic activity on CXCR2+ tumor cells." (PMID 33233582, 2020). "The results have shown no systemic toxicity, but a vaccine-induced anti-tumor response with increased IFN-γ, TNF-α, IL-5 and IL-10 production." (PMID 37513985, 2023). "Intriguingly, the expression of IL5 and IL9 was increased in ILC2s from PBMCs from NSCLC patients, but not in ILC2s from tumor tissues, compared with HD-derived PBMCs." (PMID 34194433, 2021). "There were no group differences in tumor protein concentrations of IFN-γ, IL-2, IL-4, IL-5, IL-10, and IL-12p70 (p > 0.05 data not shown)." (PMID 28811490, 2017). "Th1 polarization was demonstrated after stimulation with CTA-pulsed DCs and co-culture with tumor cells, by detecting more than 50-fold increase in IFN-γ and TNF-α production and no significant change in IL-4, IL-5, and IL-10 levels, using ELISA." (PMID 25739119, 2015). "CD4 T cells harvested from mice treated with anti-PD-L1 plus anti-LAG-3 or anti-TIM-3 also released IFN-γ when stimulated with 5T33-CIITA cells, but there was no spontaneous or tumor-induced release of IFN-γ, IL-4 and IL-5." (PMID 25614821, 2015).
tumor (continued). "Namely, multiple cytokines that promote the M1-to-M2 switch (including IL-5, IL-10, IL-17, IL-22) were higher in the serum of PyMT-bearing mice independent of the presence and absence of TAC, indicating the involvement of tumor properties in inducing this switch." (PMID 37508517, 2023). "Naturally occurring tumour‐specific HLA‐II‐restricted CD4+ T cells and those engineered to express HLA‐I‐restricted tumour TCRs have been reported to exhibit a mainly Th1 phenotype, where cells typically produce IFN‐γ, TNF‐α and IL‐2 but not IL‐4, IL‐5 or IL‐10." (PMID 27324616, 2017). "Indeed, even if some tumor antigen specific CD4 Treg clones were also found to secrete a diverse panel of cytokines such as IFN-γ, GM-CSF, TNF and IL5 or IL4 and IL10, in vitro, none of them was able to secrete IL2." (PMID 23284752, 2012).
inflammation (129 papers, 1995 to 2026). Aberrant reaction of the microcirculation characterized by movement of fluid and leukocytes from the blood into extravascular tissues. "Experimental depletion of Vγ1+ cells in an animal CRS model reduced eosinophilic inflammation and suppressed T2-associated cytokines (IL-4, IL-5, and IL-13) and GATA3 expression, indicating that defined γδ subsets can potentiate T2-biased inflammation." (PMID 41470145, 2025). "In IBD, the CD is thought to be caused mainly by the Th1 immune response, characterized by IFN-γ, TNF-α, and IL-12-mediated intestinal inflammation, while UC is associated with Th2 response, with IL-5 and IL-13 dominating in inflammation mediation." (PMID 36824689, 2023). "Severe eosinophilic asthma is characterized by chronic eosinophilic inflammation, mostly type 2 (T2) inflammation, in which IL-5 plays a central pathogenic role." (PMID 38143494, 2023). "The association of high TSLP levels with IL-5 is in agreement with extensive evidence linking TSLP with eosinophilic airway inflammation." (PMID 36245744, 2022). "Allergic asthmatic inflammation is known to be caused by the secretion of a series of Th2 cytokines (IL-4, IL-5, and IL-13) and proinflammatory cytokines (TNF-α and IL-1β)." (PMID 24312355, 2013). "The pathogenesis of SEA involves type 2 (T2) immune polarization and eosinophil-driven airway inflammation, with eosinophil maturation, activation, and survival being critically regulated by interleukin-5 (IL-5)." (PMID 41304949, 2025). "Cytokines released by Th2 cells, such as IL-4, IL-5, and IL-13, promote the proliferation and activation of eosinophils, mast cells, and goblet cells in the airways, triggering and exacerbating airway inflammation." (PMID 40993641, 2025). "Strikingly, both RAGE overexpression and SHS exposure also induced robust increases in Th2 cytokines IL-5 and IL-13—hallmarks of eosinophilic inflammation in CRSwNP." (PMID 41020862, 2025). "Treatment with GW4869 effectively alleviated the inflammatory response, whereas the instillation of additional sEVs further exacerbated nasal inflammation, with IL‐5 and ECP levels rising by 1.8‐fold and 1.4‐fold compared to the HDM group, respectively." (PMID 40999889, 2025). "The nasal tissue of NERD patients has been demonstrated to have a high expression of IL-5Rα, supporting the biological activity of IL-5 beyond eosinophils and severe sinonasal inflammation." (PMID 39404884, 2025). "The development of breads fermented with S. cerevisiae UFMG A-905 partially reduced airway inflammation, as demonstrated by the reduction in eosinophils and IL5 and IL13 concentrations." (PMID 38655128, 2024). "The allergic phenotype belongs to the T2-high endotype and is associated with the production of type 2 cytokines, such as interleukin (IL)-4, IL-5, and IL-13, and eosinophilic inflammation." (PMID 39273551, 2024). "S. cerevisiae UFMG A-905–fermented breads partially reduced airway inflammation, decreasing eosinophils and IL5 and IL13 concentrations." (PMID 38655128, 2024). "The results indicated that both treatments significantly reduced the number of CD4+CD44+ T cells, most of which were memory T cells, in addition to reducing lung inflammation and lower levels of Th2 cytokines, such as IL-4, IL-5, and IL-13." (PMID 39060348, 2024). "Several biologics have demonstrated therapeutic potential for the treatment of this pathology in which IL-4, IL-5 and IL-13 represent the major cytokines involved in the control of eosinophilic respiratory inflammation." (PMID 37763171, 2023). "Because IL-4 and IL-5 are representative Th2 cytokines that initiate chronic airway inflammation, we further investigated the levels of these cytokines in the lungs." (PMID 37107297, 2023). "Considering the role of eosinophil in pulmonary inflammation, IL-5, which is involved in the maturation and release of eosinophil, will be one of the important targets in asthmatic inflammation." (PMID 37998734, 2023).
inflammation (continued). "Other mediators, such as IL-5 (which promotes eosinophilic inflammation) and IL-9 (which stimulates the proliferation of mast cells), are also involved." (PMID 37513609, 2023). "Rapamycin treatment decreased IL-33-induced eosinophilic airway inflammation, possibly by inhibiting IL-5-producing bone marrow ILC2s." (PMID 35720347, 2022). "The literature describes that IL-10 has an important role in controlling the magnitude of pulmonary inflammation, as it regulates the production of IL-4 and IL-5 by Th2 lymphocytes, in addition to regulation of mast cell-mediated IgE activation." (PMID 35185864, 2021). "We found that the chronic eosinophilic sinonasal inflammation and type 2 immune response, including the production of IL-4, IL-5, IL-13, and CCL11, were less severe in Ifnar1−/− mice than in the WT mice." (PMID 30455684, 2018). "Progesterone aggravates the phenotype of eosinophilic airway inflammation in mice by enhancing systemic IL-5 production." (PMID 28076614, 2017). "6, 7, 8, 9, 11, 12, 34, 35, the IL-5 and IL-13 cytokines produced by activated ILC2s are essential for eosinophilic inflammation and AHR development." (PMID 27752043, 2016). "In response to acute lung inflammation FALC ILC2 rapidly produced IL-5, which was key to FALC B1-cell activation following lung inflammation." (PMID 27582256, 2016). "Previous reports demonstrated that the levels of pro-inflammatory cytokines, IL-4, IL-5, and IL-13, and airway inflammation were suppressed in mice pre-treated with SCGB1A1 or SCGB3A2 in the OVA-induced allergic airway inflammation model." (PMID 26559674, 2015). "Overall, these results highlight the synergy between GM-CSF and IL-5 in the regulation of eosinopoiesis and reveal the key role of GM-CSF in driving chronic intestinal inflammation through accumulation of activated eosinophils in the colon." (PMID 26200014, 2015). "Specifically, severe pyuria and bladder inflammation with elevated serum interleukin-5 (IL-5) and serum and urine IL-6, the neutrophil chemokine CXCL1, and granulocyte colony-stimulating factor (G-CSF or CSF3) at 24 hpi are predictive of chronic infection." (PMID 26125048, 2014). "The direct administration of IL-33 to mouse lung induces IL-5-producing T cells, thus exacerbating allergen-induced airway inflammation." (PMID 24586149, 2014). "In an experimental mice model of pulmonary eosinophilic inflammation, subcutaneous 1,25(OH)D injections abrogated IL-5 production in bronchoalveolar lavage fluid." (PMID 22405472, 2012). "We aimed to evaluate the therapeutic effect of a neutralizing anti-IL-9 antibody in a mouse model of airway eosinophilic inflammation and compared any such effect with anti-IL-5 treatment." (PMID 15823208, 2005). "IL-4 has emerged as a central target, not only for B cell IgE production, but also in the commitment of both CD4+ and CD8+ T cells to cells with Th2 effector function capable of secreting IL-5 resultlng in eosinophilic inflammation." (PMID 18475645, 1995). "IL-5 is a key cytokine involved in eosinophilic inflammation and allergic responses, and the development of eosinophilic airway inflammation in a mouse bronchial asthma model are attenuated in transgenic mice by the overexpression of enzymatically inactive Ras molecules in T cells." (PMID 40514730, 2025). "In the context of ALI, IL-5-driven eosinophilic inflammation can lead to increased vascular permeability and damage to the alveolar epithelium, contributing to the characteristic pulmonary inflammation and hypoxemia of ALI." (PMID 40872499, 2025). "IL-5 shares receptor components with IL-3 and granulocyte–macrophage colony-stimulating factor (GM-CSF), and it is involved in preventing eosinophilic apoptosis during allergen-induced airway inflammation." (PMID 40563358, 2025).
inflammation (continued). "This epithelial injury triggers the release of alarmins IL-33 and TSLP, activates innate lymphoid cell types 2 (ILC2) and T cells, and promotes IL-5/IL-13-driven eosinophilic and interleukin-17A-mediated neutrophilic inflammation—resulting in mixed airway inflammation." (PMID 41450494, 2025). "These βc cytokines, including IL‐3, GM‐CSF, and IL‐5, play a substantial role in regulating a broad spectrum of inflammatory responses, both accelerating pathogen clearance and potentially contributing to the pathogenesis of chronic inflammation." (PMID 39697159, 2024). "Similarly, in a model of allergic airway inflammation induced by Timothy grass pollen extract, the administration of MALP-2 (TLR2/6 agonist) during the allergen challenge reduced eosinophilic inflammation and IL-5 and IL-10 production by lymph nodes." (PMID 39273551, 2024). "Early life hyperoxia exposure enhances innate lymphoid cell (ILC2) function by increasing the expression of IL-33, and ILC2s produce type 2 cytokines such as IL-5, IL-13, and mediators involved in tissue repair, leading to eosinophilic airway inflammation and airway remodeling." (PMID 37485534, 2023). "Using a murine model exhibiting persistent airway inflammation we sought to understand the effect of PI3Kδ inhibition, montelukast and anti-IL5 antibody treatment on IL33 expression, group-2-innate lymphoid cells, inflammatory eosinophils, and goblet cell metaplasia." (PMID 34920698, 2021). "It has been well documented that IL-4 and IL-5 play critical roles in airway inflammation by mobilising and activating eosinophils, which lead to the release of pro-inflammatory mediators such as major basic protein and cysteinyl leukotrienes, which have the capacity to cause AHR." (PMID 33784348, 2021). "Collectively, these data show that papain induced eosinophilic inflammation is dependent on IL-5 and that IL-5 levels might regulate ST2 expression on bone marrow eosinophils which in turn drives the maturation of eosinophil within the bone marrow." (PMID 32582171, 2020). "For example, it has been shown that IL-4 and IL-5 are anti-inflammatory in models of bleomycin-induced airway inflammation by regulating T cell and myeloid cell expansion, respectively but the molecular mechanisms are unknown." (PMID 32103153, 2020). "Therefore, the positive correlation among IL-25, IL-5 and IL-13 indicates that IL-25 plays a role in the increase of Th2-type cytokines (IL-5 and IL-13) that induces asthmatic airway inflammation and promotes Th2-type adaptive immune responses." (PMID 27617447, 2016). "IL-5 and IL-13 are TH2 cytokines associated with the development of airway inflammation in mice and humans; the observed increase in these proinflammatory cytokines in Cbl-b−/− mice is suggestive of exacerbated TH2 cell responses to aerosol challenge during acute inflammation." (PMID 26635806, 2015). "This is the first study showing that eosinophiluria, urinary ECP and IL-5 may be useful as biomarkers of renal inflammation in SLE patients." (PMID 25520739, 2014). "Mice that received Th2 cells secreted IL-4, IL-5 and IL-9 and up-regulated Arg1, Eotaxin (Ccl11) and Gob5 (Clca3) within the lung, characteristic of Th1 or Th2-mediated airway inflammation." (PMID 23825948, 2013). "Importantly, both IL-33 and IL-25 could activate ILC2, leading to production of IL-5 and IL-13, which mediates lung inflammation." (PMID 34970267, 2021). "In addition, the production of IL-13/IL-5 promoted by nuocytes induced airway inflammation." (PMID 27617447, 2016). "Airway inflammation in asthma is heterogeneous and may be dominated by an allergen-specific acquired immune response with IL-5 mediated eosinophilic inflammation, or a dysregulation of innate immune responses involving IL-8-induced neutrophilic airway inflammation." (PMID 23948757, 2013).